GFAP (glial fibrillary acidic protein)
Diseases named in the same sentence as GFAP in open-access papers (continued):
Sharing a sentence is not in itself a finding about the gene and the disease.
tumor (continued). "However, in comparison to sham-irradiated controls, 3 Gy or 15 Gy X-ray irradiation led to a significant increase in GFAP mRNA expression in assembloids or co-cultures of organoid slices with GFP+/c-MYChigh tumor-like cells, respectively, when compared to the corresponding sham-irradiated controls." (PMID 40917877, 2025). "Previous research has suggested that positive GFAP may indicate a malignant tendency of the tumor." (PMID 39066950, 2024). "This tumour is usually GFAP-positive but may lack OLIG2 and SOX10." (PMID 39126064, 2024). "However, rodent models indicated that loss of GFAP does not contribute directly to tumor progression and its prognostic relevance is not well-established." (PMID 35073955, 2022). "Although it is unclear whether glia-derived WNTs are implicated in tumour formation in this model, together, these studies support the central role of the GFAP+ (but not the PLP1+) subpopulation of EGCs in intestinal epithelial health 20, 21••, 38•." (PMID 35533467, 2022). "Our results showed that xenograft tumors contained a proportion of the tubule-like structures composed of endothelial/glial phenotypic (vWF+/GFAP+) cells, suggesting that U118 cells could directly transdifferentiate into or fuse with endothelial cells to participate in tumor angiogenesis." (PMID 34660561, 2021). "The GFAP staining is useful for determining whether a tumor of glial origin." (PMID 34869589, 2021). "However, some areas of tumor were immunonegative for GFAP, except a few tiny glial processes." (PMID 32650833, 2020). "Immunofluorescence (IF) analysis of astrocytes (GFAP) and microglia (Iba1) showed increased activation of both cell types surrounding tumor foci, without associated DTX-specific changes, corroborating a well working BM-model and nicely mimicking BM distribution usually observed in patients." (PMID 31665089, 2019). "In addition to RNA-Seq experiments, we also used quantitative real-time PCR (qPCR) to analyze Etv5 RNA expression in independently-generated non-neoplastic (Nf1flox/flox; abbreviated N for normal) and tumor-bearing (Nf1flox/null GFAP-Cre; “OPG-1”) optic nerves." (PMID 29787563, 2018). "In addition, the high levels of GFAP in VTC-037/GSCs may explain the failure of this line in tumor formation in mice." (PMID 27863440, 2016). "In addition, also note some MMP9 expression in the tumor cores, which may reflect differentiation of cells and is in agreement with the presence of GFAP." (PMID 26700636, 2015). "Protein levels for HBEGF, human tumor cell markers (vimentin), EGFR and astroglial differentiation markers (GFAP, Meteorin) were determined by Western Blot in all treatment groups." (PMID 41181988, 2026). "On initial biopsy, GFAP negativity and aberrant expression of other markers, including the melanosomic marker HMB45, led to uncertainty regarding tumor lineage." (PMID 40610013, 2026). "We observed a significant increase over time in the interactions between SOX2/OLIG2 high tumor cells and different tumor cell populations, including p-TYR high and translating GFAP- tumor cells." (PMID 41568176, 2026). "Next, using CRISPR/Cas9 technology to knockout Olig1/2, we found that astrocyte differentiation markers such as GFAP, SOX9, and HOPX were preserved, but tumor cell proliferation was significantly diminished." (PMID 40428395, 2025). "Despite declining BCAN, GFAP, and VEGF-A, T1-gadolinium–positive tumor volume increased until POD552, likely indicating pseudoprogression." (PMID 39786485, 2025). "The CAR-treated hCD147TG tumor-bearing mice had significantly higher GFAP activation than the naive NK+T and PBS-treated tumor-bearing mouse groups." (PMID 40160933, 2025). "The tumor cells expressed NSE and cytokeratin AE1/AE3, but were immunohistochemically negative for synaptophysin, chromogranin A, calcitonin, S-100 protein, GFAP, NFH, and MAP-2, which in our opinion supports the diagnosis of NEC." (PMID 39974159, 2025).
tumor (continued). "The GFAP and GFHP scaffolds promoted the elongated shape of tumor cells compared with the GF scaffold, suggesting the high biocompatibility of natural polymer-based scaffolds and the benefits of functionalizing the scaffolds’ composition." (PMID 39940603, 2025). "Histological examination confirmed an infiltrative glial lesion: immunoreaction positive for GFAP and for oligodentrocyte transcription factor (OLIG2) in tumor cells." (PMID 40277798, 2025). "Immunohistochemistry extrapolated from GFAP immunoreactivity and EMA-positive and ultrastructural characteristics, the tumor exhibited glial and ependymal differentiation and was described as monomorphous angiocentric glioma." (PMID 39098857, 2025). "The results of the biocompatibility and cytotoxicity assays indicated the overall good biocompatibility of the unenriched scaffolds (GF, GFAP, and GFHP) in contact with both the normal MCF-12A and tumor MDA-MB-231 cells." (PMID 39940603, 2025). "The expression of tumor major histocompatibility complex (MHC) classes I and II was examined after treatment; 83.8%, 75.3% and 72.7% of GFAP+/SOX2+ GBM cells expressed MHC class I, MHC class II or both MHC classes I and II, respectively." (PMID 40016450, 2025). "Evidence suggests that tumor cells release cytokines (e.g., IL-6) to activate astrocytes via JAK/STAT and GFAP signaling." (PMID 40149331, 2025). "Stimulation of IL-1β secretion by GF + PTX (p < 0.0001) and GFAP + PTX (p < 0.0001) between 12 h and 24 h of incubation suggests the consequences of the prolonged exposure of tumor cells to the chemotherapeutic agent." (PMID 39940603, 2025). "Glial fibrillary acidic protein (GFAP) positivity indicates astrocytic differentiation, while high Ki-67 (proliferation index) values reflect tumor aggressiveness." (PMID 40937216, 2025). "In the case of the MDA-MB-231 tumor cells, the exposure to GF + PTX and GFAP + PTX led to a significant increase in the H2O2 concentration after 12 h of incubation." (PMID 39940603, 2025). "Within the 37-gene-set, we highlight GPM6A (Glycoprotein M6A), ABAT (4-Aminobutyrate Aminotransferase), GFAP (Glial Fibrillary Acidic Protein), and AQP4 (Aquaporin-4), known to play roles in tumor invasion and progression within various cancers." (PMID 40575267, 2025). "Among these, we found some key genes previously reported to be involved in tumor invasion and progression in other types of tumors, such as GPM6A, ABAT, GFAP, and AQP4." (PMID 40575267, 2025). "Astrocytic projections (GFAP+) in MB tissue were identified in three different spatial patterns: adjacent to the endothelium (as part of the BBB), interspersed among tumor cells, or simultaneously in both locations." (PMID 40805120, 2025). "Immunohistochemical staining demonstrated diffuse glial fibrillary acidic protein (GFAP) positivity and S100 expression, with strong SOX10 nuclear labeling in tumor cells." (PMID 41458616, 2025). "In concordance with transcriptomic data using GFAP to depict tumor purity, abundance of PTPRZ1+ cells correlated positively with GFAP+ cells." (PMID 39893177, 2025). "As expected, caspase-1 expression increased as a consequence of the tumor cells’ contact with the GF + PTX and GFAP + PTX scaffolds compared with the normal cells and unenriched scaffolds, GF and GFAP (p < 0.01 and p < 0.001, respectively)." (PMID 39940603, 2025). "The tumor cells expressed CD99, synaptophysin, CD56, MUC4, and EMA (focal), but not AE1/AE3, S100, smooth muscle actin, desmin, CD34, chromogranin A, GFAP, NKX2-2, PAX7, and INSM1." (PMID 39249507, 2024). "The cell counts of GFAP and IBA1 in different groups demonstrated significantly lower GFAP+ cells and increased IBA1+ cells in both tumor regions for shHTR2C and shGABRG2." (PMID 38884167, 2024). "The tumor was immunonegative for EMA, GFAP, IDH 1, inhibin, neurofilament, AE1/AE3, and melanoma cocktail." (PMID 39444783, 2024). "However, whether METTL8 and GFAP co-localize in tumor cells or astrocytes requires further study." (PMID 38824202, 2024).
tumor (continued). "Tumor cells are intermingled with reactive inflammatory T lymphocytes, including CD3 and CD8 positive, reactive glial fibrillary acidic protein (GFAP)-positive astrocytes, and CD68 positive macrophages." (PMID 39186169, 2024). "Reactive astrocytosis with typical overexpression of GFAP and vimentin (VIM) is commonly found at the boundary of the tumor bulk and in the peritumoral microenvironment." (PMID 38671983, 2024). "Human astrocytes can be identified for the expression of the glial fibrillary acidic protein (GFAP), which increases in response to injury, even though its labeling appears weak and diffused in the tumor area." (PMID 38671983, 2024). "Multiplexed IF analysis focused on GAMs (murine IBA1, TMEM119, and CD206), astrocytes (murine GFAP), CAR T cells (human CD3), and tumor surface/proliferation markers (human EGFRvIII, and Ki67) within and surrounding tumor regions." (PMID 39521782, 2024). "Analysis using immunohistochemistry shows the presence of cytokeratins, S100 protein, GFAP, Vimentin, and SMA staining, indicating the tumor's mixed epithelial and stromal composition." (PMID 39221300, 2024). "Both tumor models reveal a high degree of overlap between GFAP (red) and EGFP (green), with minimal overlap between tumor cells (gray) and EGFP, indicating that EGFP-positive cells are likely astrocytes." (PMID 38997283, 2024). "Immunohistochemistry testing of tumor cells was positive for S100, CD10, glial fibrillary acidic protein (GFAP), and desmin expression." (PMID 39070435, 2024). "Medium expression of GFAP and limited expression of S100 and OLIG2 were detected in the NHA/HRasV12/TRIM24 S767/768A‐derived tumor xenografts." (PMID 38828688, 2024). "As expected, double immunostain combining GFAP and EBF3 showed a selective EBF3 expression in the GFAP-negative MB tumor component, suggesting co-existence of two different major tumor subclones with either glial or early neuronal differentiation." (PMID 36941703, 2023). "A total of 76 circular ROIs, 300 μm in diameter, were segmented into CD45+ (Immune), GFAP+ (Astrocyte/Tumor), or CD45−/GFAP−." (PMID 37377888, 2023). "Here, we demonstrate that GCS-enriched spheres from WG14 expressed significantly higher levels of OLIG2 and lower levels of astrocytic (GFAP) and neuronal (β-Tubulin III) markers as compared with the adherent tumor cells." (PMID 36900355, 2023). "Immunostaining for glial fibrillary acidic protein (GFAP) showed widespread labelling in the cytoplasm and processes of the tumor cells in IEE." (PMID 37376821, 2023). "Compared with that in control mice (P53f/f; R26-MET404-flag+/+; GFAP-Cre, MST 48.35 weeks, often died due to mouse or subcutaneous tumours), the overall survival was remarkably shorter in MET404 KI mice (MST 29.25 weeks, all died of CNS tumours)." (PMID 37491377, 2023). "Within the murine tumor, senescent cells were of distinct types, and included either malignant (GFP+) tumor cells, glial cells (GFAP+, OLIG2+), or microglia/macrophage (IBA1+)." (PMID 36707509, 2023). "Immunostaining of TK-EPN862 tumor cells was consistent with the features of EPN, including negative staining for OLIG2 and synaptophysin, positive staining for GFAP, and intracytoplasmic dot-like positivity for EMA." (PMID 36937401, 2023). "Immunostaining has shown positive staining for glial markers such as GFAP and Olig2, albeit with weak or focal expression, but CD34 expression was notably prominent and consistently observed across tumor cells and neuronal elements." (PMID 38137148, 2023). "The tumor showed extensive microcalcifications and cells with oval, nuclei and a clear perinuclear halo (A), positive immunostaining for OLIG-2 (B), GFAP (C), and CD34 (D), and intermingled Neu-N-positive neurons (E)." (PMID 37409721, 2023). "Even at early time points, AAV6 predominantly transduces astrocytes identified as GFAP + RFP− (70–80% EGFP + cells), with limited EGFP expression observed in RFP + tumor cells (< 15%)." (PMID 38014191, 2023).
tumor (continued). "The upregulation of GFAP and CX-43 in astrocytes, and the expression of MMP-2 by the tumor cells, promote tumor infiltration." (PMID 35205842, 2022). "In this figure, we can identify the location of the tumor (GFP+ cells) containing parenchymal blood vessels (TdTomato+), and astrocytic processes (GFAP+)." (PMID 35750880, 2022). "To access the differentiation capacity of decitabine, as a DNA methyltransferase inhibitor of tumour cells, we stained cells treated with TMZ in combination with VPA or decitabine for the astrocyte marker GFAP." (PMID 35625011, 2022). "To further verify the involvement of astrocytes within the tumor, we performed immunostaining against GFAP and the IUE marker and our results showed GFAP-positive labeling in IUE cells." (PMID 36538906, 2022). "Tumor cells within the PD-GBO form a morphological interconnecting tumor network proficient for nestin, Gap43, Connexin 43, and the astrocytic marker GFAP." (PMID 35743016, 2022). "In contrast, the LV-proximal tumor animals contained localized areas of extreme LV wall disruption, where ependymal cells were lost and GFP + GBM cells and several GFAP + astrocytes had direct contact with the LV lumen." (PMID 35821139, 2022). "Using high power resolution in the tumor area, we observed that GFAP expression was lower in the internal core of the tumor than in the peripheral area, CD34-positive vessels were surrounded by GFAP-positive astrocytes, and AQP4 was weakly expressed." (PMID 35083148, 2021). "Nevertheless, immunostaining for KMO showed that the protein is mainly localized to GFAP+ cells, indicating that tumor cells of the astrocytic lineage express KMO, but also in a heterogeneous way between different tumor samples." (PMID 34440798, 2021). "The result of immunofluorescence showed that these tumor spheres were able to differentiate into MAP2+ neurons, O4+ oligodendrocytes and GFAP+ astrocytes." (PMID 33614649, 2021). "Microglia cells and astrocytes localized primarily at the periphery of the tumor in DMSO-treated cells with little co-localization of TSPO and GFAP." (PMID 33500706, 2021). "In all injection sites, multicellular tumor-like formations contained foci with positive cells for AFP, ASM, or GFAP." (PMID 34831039, 2021). "The majority of control tumor cells appear mesenchymal with pervasive expression of CD44 and VIM and an astrocytic subpopulation expressing GFAP at high levels." (PMID 33975634, 2021). "Analyses of in vivo orthotopic tumor also indicated that 100% of SOX2+ or Nestin+ GSLCs were BPA+, whereas only 36.9% of glial fibrillary acidic protein (GFAP)+ DCs were BPA+." (PMID 33086625, 2020). "Some glial-shaped cells and tumor cells were found double positive for ALDH1A3 and GFAP (arrows, respectively)." (PMID 32680476, 2020). "Importantly, given that GFAP is expressed in a subset of ileal epithelial cells, the reduced tumor burden observed in the Gfap-tk ApcMin/+ mice could be attributed to direct killing of GFAP+ tumor epithelial cells rather than to the loss of enteric glia." (PMID 33282743, 2020). "Overall, our enteric glia depletion models indicate that GFAP+ enteric glia play a critical tumor-promoting role in the development of CRC, as depletion of the enteric glia dramatically reduced tumor burden in AOM/DSS mice." (PMID 33282743, 2020). "In our opinion, they remain visible for a long time in the proliferative tumor due to their GFAP positivity and NG2/CSPG4 expression, undergoing the pathoplastic influence from tumor cells, mainly in relation to vessels." (PMID 32599896, 2020). "The BCL2, IL1-β, GFAP and KI67 levels in C6 tumor cells exposed with Ator and MSCs significantly activated compared to control sample." (PMID 32981013, 2020).
tumor (continued). "In tumor nerves with PNI there is an increase in Schwann cells (GFAP+, Glial fibrillary acidic protein) and they intercalate with cancer cells by direct contact through NCAM1 (neural cell adhesion molecule 1)." (PMID 32555170, 2020). "Both the patient and the PDX tumours were positive for OLIG2, nestin, vimentin and GFAP, with focal Ki-67 proliferative indices of up to 25% in the patient tumour and 40% in PDX tumours, respectively." (PMID 33053751, 2020). "Genetic testing in GFAP CTC-DNA by sanger sequencing, q-PCR and NGS methods indicated that the isolated CTCs (GFAP+/EGFR+) are the related tumor cell." (PMID 33208163, 2020). "Immunohistochemistry of tumor samples from an orthotopic mouse model by double staining of BPA and a stem marker (SOX2 or Nestin) or differentiation marker, GFAP, revealed that all SOX2- or Nestin-positive GSLCs were also positive for BPA." (PMID 33086625, 2020). "Altogether, a significantly decreased expression of MCT1 (p: 0.025) and a significantly increased expression of GFAP (p: 0.010), β-catenin (p: 0.039), KLF4 (p: 0.035) and OCT4 (p: 0.026) was detectable at the edge of the tumor compared with the center." (PMID 32872409, 2020). "Both the astrocyte-specific glial fibrillary acidic protein (GFAP) and the end-foot marker aquaporin-4 (AQP4) were localized between the partly or completely extravasated tumour cell and the capillary endothelium." (PMID 31426859, 2019). "Serial tumor tissue sections were taken, and HAS3, differentiation markers (GFAP and TUBB3), and an autophagic marker (LC3) were detected by IHC." (PMID 31274246, 2019). "For this, they recognized many GSC markers that can be used for the differentiation of these tumor cells such as human CD133, ATP-binding cassette subfamily G member 2 (ABCG2), glial fibrillary acidic protein (GFAP), Notch 1, and Sonic hedgehog (SHH)." (PMID 30609771, 2019). "In support, tumor samples harvested from the combination of pacritinib and TMZ showed the lowest level of STAT3, Sox2, PDCD4, and miR-21-5p and an increased level of GFAP." (PMID 31269723, 2019). "Among the overexpressed genes, PTGDS (13.761-fold) had the highest log2 fold change in tumor versus non-tumor tissues, followed by TNFRSF18 (13.387-fold), glial fibrillary acidic protein (GFAP) (12.296-fold), BARHL1 (12.175-fold), and KIF26A (11.719-fold)." (PMID 30195786, 2018). "The identities of both primarily cultured p-GBM tumor cells were confirmed by analyzing the expression of specific markers (sox2, nestin for GBM neural stem cells; GFAP, NeuN for differentiated GBM tumor cells)." (PMID 29527330, 2018). "Several recent studies have indicated that GFAP may be useful as a broader biomarker, in addition to being a prognosticator, for patients with different types of solid tumors wherein increased expression of GFAP often marks tumor cells with a tendency to mature, signaling a better prognosis." (PMID 30534564, 2018). "The immunofluorescence staining of the GBM tumors with tumor specific markers evaluated the impact of the brain microchip’s microenvironment on the expression of Nestin, VEGFR2 and GFAP." (PMID 30337660, 2018). "Both the normal nerve cells and tumor cells also stained positive for PGP9.5, NSE, calretinin, and GFAP." (PMID 29329562, 2018). "One [GFAP-tTA;TRE-SMOA1] mouse survived beyond 200 days with a very large tumor mass identified post-mortem." (PMID 30360486, 2018). "We demonstrated that GFAP/CD133+CD90+/CD44+ EPN cells maintained key histopathological and growth characteristics of the original patient tumor." (PMID 29774098, 2018). "In turn, the expression of Glial Fibrillary Acidic Protein (GFAP) as a marker of differentiated astroglial cells, and nestin as a marker of neuronal stem cells, was evaluated in the tumor samples of treated animals." (PMID 30208561, 2018).